TIMP2 (TIMP metallopeptidase inhibitor 2)
Diseases named in the same sentence as TIMP2 in open-access papers (continued):
Sharing a sentence is not in itself a finding about the gene and the disease.
osteosarcoma (13 papers, 2009 to 2023). A usually aggressive malignant bone-forming mesenchymal neoplasm, predominantly affecting adolescents and young adults. "The result showed that the “TCC” haplotype in the TIMP2 (consisted of rs2277698, rs2009169, and rs7342880) was associated with decreasing the osteosarcoma risk (OR = 0.66, 95% CI: 0.48–0.96, P = .031)." (PMID 33725949, 2021). "The polymorphisms of TIMP2 (rs2277698 and rs4789936) were significantly associated with decreasing the osteosarcoma risk." (PMID 33725949, 2021). "Our results show that the rs2277698 and rs4789936 in the TIMP2 were associated with decreasing the risk of osteosarcoma." (PMID 33725949, 2021). "In addition, the haplotype “Trs2277698Crs2009169Crs7342880” of TIMP2 was associated with decreasing the osteosarcoma risk." (PMID 33725949, 2021). "This study identified that the rs2277698 and rs4789936 in the TIMP2 were associated with decreasing the risk of osteosarcoma in Zhejiang populations, and found the expression level of TIMP2 in osteosarcoma histiocytes was significantly higher than the normal histiocytes." (PMID 33725949, 2021). "This study aimed to explore whether TIMP2/TIMP3 polymorphisms influenced the osteosarcoma risk." (PMID 33725949, 2021). "TIMP2 is a lncRNA that interacts with miR-182 to drive osteosarcoma invasion in an MMP MMP-dependent way." (PMID 37245177, 2023). "The results indicate that the expression level of TIMP2 in osteosarcoma histiocytes was significantly higher than the normal histiocytes." (PMID 33725949, 2021). "The most frequent haplotype was used as reference, haplotype analysis of genes TIMP2 and TIMP3 detected significant association with the risk of osteosarcoma." (PMID 33725949, 2021). "The immunohistochemistry results showed that the expression of TIMP2 is obvious higher in osteosarcoma histiocytes than in the normal histiocytes." (PMID 33725949, 2021). "We found that the expression level of TIMP2 in osteosarcoma histiocytes was significantly higher than the normal histiocytes." (PMID 33725949, 2021). "In the present case–control study, we investigated the associations between 10 SNPs in TIMP2 and TIMP3 genes and osteosarcoma risk in Zhejiang population." (PMID 33725949, 2021). "In thisin vitrostudy, the NM significantly inhibited secretion of u-PA and MMP-2 and/or -9 and increased secretion of TIMP-2 in osteosarcoma and rhabdomyosarcoma cells, suggesting its potential in modulating cancer invasion and metastasis." (PMID 23900236, 2013). "TIMP-2 was shown to stimulate proliferation in human cells, including osteosarcoma cells, fibroblasts, and A549 lung adenocarcinoma cells." (PMID 19627587, 2009). "Also, UCA1 interacts with miR-182, leading to osteosarcoma via cellular proliferation and metastasis in a TIMP2-dependent manner." (PMID 37245177, 2023). "Therefore, we performed a case-control study to analyze the association between the TIMP2 and TIMP3 genes and the risk of osteosarcoma from the teenagers in Zhejiang Province." (PMID 33725949, 2021). "Additionally, we identified that TIMP2 was identified as direct target of miR-93, and which mediates its promoted function in osteosarcoma cells." (PMID 31383784, 2019). "As expected, a significant positive correlation was found between the secretion of u-PA and MMP-2/MMP-9 and a significant negative correlation between u-PA and TIMP-2 and between MMP-2/MMP-9 and TIMP-2 secretion by NM treatment of osteosarcoma and rhabdomyosarcoma cells." (PMID 23900236, 2013). "TIMP2 is involved in matrix degradation and invasion, and is down-regulated in Motif 1 cell lines in this study, which is consistent with its role in inhibiting matrix metalloproteinases, and agrees with the inverse correlation shown between S100A4 and TIMP2 in osteosarcoma cells." (PMID 20041153, 2009). "In osteosarcoma, piperine inhibited cell migration by reducing the expression of MMP2 and MMP9 and increasing the expression of TIMP1 and TIMP2." (PMID 36678600, 2023).
osteosarcoma (continued). "The expression of the TIMP2 and TIMP3 genes in osteosarcoma histiocytes was analyzed by immunohistochemistry." (PMID 33725949, 2021). "In addition, we first used IHC to detect the expression of the TIMP2 and TIMP3 gene in normal histiocytes and osteosarcoma histiocytes." (PMID 33725949, 2021). "Additionally, in osteosarcoma cells, it also possesses the anti-metastatic activity by down-regulating the MMP-2 and MMP-9 secretions and increasing the TIMP-1 and TIMP-2 expressions via Akt-dependent and p38 pathways." (PMID 34068885, 2021).
colon cancer (11 papers, 2011 to 2024). "Apelin, an endogenous peptide implicated in the progression of multiple cancers, including lung, hepatocellular, and colon cancer, facilitates TIMP-2-dependent PCa cell migration and invasion." (PMID 38790213, 2024). "In summary, TDG interacts with DNMT3A to promote ubiquitination degradation, induces the hypomethylation of the TIMP2 promoter, increases TIMP2 expression, and significantly inhibits the migration and invasion abilities of human colon cancer cells." (PMID 35414793, 2022). "We confirmed that proliferation and invasion of colon cancer cells are regulated in vitro and in vivo by miR‐373 through targeting of the tumor suppressors TIMP2 and APC." (PMID 32118353, 2020). "SiRNA-mediated knockdown of TIMP2 in HCT-116 colon cancer resulted in a reduction of invasion of HCT-116 cells in vitro." (PMID 30473751, 2018). "The effect of IL-1β and IP6 on the expression of mRNA of MMP-1, MMP-2, MMP-3, MMP-9, MMP-10, and MMP-13 and that of their tissue inhibitors TIMP-1 and TIMP-2 in colon cancer cells using real-time QRT-PCR assay was determined." (PMID 22415590, 2012). "Here, we also found that TIMP2 was regulated via methylation in human colon cancer cells." (PMID 35414793, 2022). "Furthermore, the ChIP, MSP, and rescue experiments results confirmed that TDG accelerated the degradation of DNMT3A and significantly regulated the transcription and expression of TIMP2, thereby affecting the migration and invasion of human colon cancer cells." (PMID 35414793, 2022). "A role for APC in the development of colon cancer has been reported; thus, we focused on TIMP2." (PMID 32118353, 2020). "DNMT3A overexpression partially rescued the TDG-induced decrease in the migration and invasion abilities of colon cancer cells, and rescued the TDG-induced increase in the TIMP2 expression." (PMID 35414793, 2022). "Our study reveals that NE promotes colon cancer cell proliferation and metastasis by activating the NE–CREB1–miR‐373 axis and demonstrates that the targets of miR‐373, TIMP2 and APC, mediate these NE‐induced effects." (PMID 32118353, 2020). "We have demonstrated that NE promotes the progression of colon cancer via CREB1 activity‐dependent transcription, enhancing the expression of oncogenic miR‐373 and reducing the expression of the miR‐373 targets APC and TIMP2." (PMID 32118353, 2020). "NE promotes the progression of colon cancer via CREB1 activity‐dependent transcription, enhancing the expression of oncogenic miR‐373 and reducing the expression of the miR‐373 targets APC and TIMP2." (PMID 32118353, 2020). "Therefore, we propose that TDG can inhibit the migration and invasion abilities of colon cancer cells by reducing their level of DNMT3A, decreasing the TIMP2 promoter methylation, and increasing the expression of TIMP2." (PMID 35414793, 2022). "Treatment with recombinant TIMP-1 or TIMP-2 showed a trend, although not statistically significant, to decrease CD49a+ and TIM-3+ expression and increase NKG2D in peripheral blood NK cells exposed to conditioned media from colon cancer cell lines." (PMID 34638439, 2021). "Therefore, we next determined levels of endogenous miR-21 and ECM mediators in colon cancer cell line LS174 by RT-qPCR, and found a positive correlation between miR-21 and ECM mediators MMP-2, MMP-9, and MMP-11, but not between miR-21 and ECM inhibitor TIMP-2." (PMID 32427870, 2020).
heart failure (11 papers, 2014 to 2025). Inability of the heart to pump blood at an adequate rate to meet tissue metabolic requirements. "We found that galectin-3 and MMP-2 were significantly associated with global cardiac fibrosis, even after adjusting for confounding risk factors, whereas TIMP2 and NT-proBNP were significantly associated with the aggravation of heart failure symptoms." (PMID 30413105, 2018). "Several biomarkers—including IGFBP-1, IGFBP-2, IGFBP-3, FGF-23, MMP-2, MMP-7, TIMP-2, and RAGE/AGE—were significantly elevated in patients with cardiac involvement and independently associated with either heart failure decompensation or death/transplantation." (PMID 41226753, 2025). "The lack of mitral TIMP2 expression is associated with increases in cardiovascular death and heart failure following MV surgery." (PMID 24475101, 2014). "TIMP-2 has the specific ability to stimulate collagen synthesis, and MMP-9 seems to be more activated in heart failure with reduced ejection fraction and dilated cardiomyopathies than MMP-2." (PMID 36005418, 2022). "RT-qPCR showed that expression levels of the heart failure markers (ANP and BNP) and the fibrotic markers (α-SMA, TIMP2, and MMP9) were significantly higher in the DAC group than in the sham group." (PMID 34150870, 2021). "In atrial biopsies, the downregulation of TIMP-2 and upregulation of MMP-2 correlates with the development of sustained AF in patients with cardiomyopathy and heart failure." (PMID 34203369, 2021). "Among Tc+ individuals, those with cardiac insufficiency had higher levels of BNP, NTproBNP, troponin I, MMP-2, TIMP-1, and TIMP-2 than those with normal ejection fraction and left ventricular diameter." (PMID 25275382, 2014). "Bio-ADM: Bioactive adrenomedullin; CA125: Carbohydrate antigen 125; eGFR: Estimated glomerular filtration rate; HF: Heart failure; IGFBP7: Insulin-like growth factor binding protein 7; sST2: Soluble Suppression of Tumorigenicity-2; TIMP-2: Tissue inhibitor of metalloproteinases-2." (PMID 41157213, 2025). "TIMP2 is highly expressed in the myocardium and has the dual actions of activating pro-MMP2 and blocking the activation of MMP2, which inhibit angiogenesis and the development of heart failure." (PMID 31182988, 2019).
lung adenocarcinoma (11 papers, 2009 to 2026). A carcinoma that arises from the lung and is characterized by the presence of malignant glandular epithelial cells. "TIMP-2 expression in lung adenocarcinomas was significantly associated with the alteration of driving proto-oncogene tyrosine-protein kinase (c-Src) and phosphatidylinositol 3-kinase/protein kinase B (PI3-kinase/AKT pathways)." (PMID 29393911, 2018). "On the contrary, high TIMP-2 expression was noted in lung adenocarcinomas and was associated with poor prognosis." (PMID 29393911, 2018). "To evaluate the association between the growth-stimulatory activity of TIMP-2 and lung adenocarcinoma prognosis, we collected gene expression data from Gene Expression Omnibus (GEO) and TCGA." (PMID 26556867, 2015). "Furthermore, we showed that high TIMP-2 expression in lung adenocarcinomas is associated with a worse prognosis from multiple cohorts, especially for stage I lung adenocarcinoma." (PMID 26556867, 2015). "In addition, by analyzing gene expression data from lung adenocarcinoma tissues, we showed that TIMP-2 expression is associated with a worse prognosis, especially in pstage I lung adenocarcinoma, from multiple cohorts." (PMID 26556867, 2015). "Additionally, we performed a genome-wide survey of gene-expression data to evaluate the association of TIMP-2's growth-stimulatory activity with lung adenocarcinoma prognosis in multiple independent cohorts." (PMID 26556867, 2015). "While TIMPs were initially considered anti-cancer proteins, Bourboulia found that TIMP-2 overexpression stimulates lung adenocarcinoma cell proliferation." (PMID 40607416, 2025). "TIMP2 over expression has also been associate with reduced MDSC recruitment, tumor volume and angiogenesis in a lung adenocarcinoma model." (PMID 34066355, 2021). "First, we analyzed the expression of TIMPs in lung adenocarcinoma in the TCGA database and found that only TIMP2 and TIMP3 expression were significantly down-regulated in tumors compared to normal controls." (PMID 27058897, 2016). "Distinct separation of OS and RFS survival curves based on TIMP2 expression was confined to patients with pathological stage I (pstage I) lung adenocarcinoma (p < 0.001)." (PMID 26556867, 2015). "Treating the other lung adenocarcinoma cell lines with 250 pM of either TIMP-2 or TIMP-2 C72S stimulated 1.4-fold to 1.7-fold increases in cell proliferation in a statistically significant fashion (p < 0.05) when compared with untreated cells." (PMID 26556867, 2015). "Patients with pstage I lung adenocarcinoma and high TIMP2 expression had a similar survival curve to those patients with pstage II lung adenocarcinoma." (PMID 26556867, 2015). "In previous reports, TIMP-2 stimulated A549 lung adenocarcinoma cell proliferation at concentrations of 10–50 pM." (PMID 26556867, 2015). "Taken together, our results demonstrate that TIMP-2 stimulates lung adenocarcinoma cell proliferation through c-Src, FAK, PI3-kinase/AKT, and ERK1/2 pathway activation in an MMP-independent manner." (PMID 26556867, 2015). "We also tested the correlation between TIMP-2 and the alteration of driving genes through integrated analysis of The Cancer of Genome Atlas (TCGA) for lung adenocarcinoma." (PMID 26556867, 2015). "It has also been reported to promote angiogenesis in lung adenocarcinoma metastasis by targeting TIMP2/3 through cancer-derived exosomes, and overexpression of miR-197-3p may promote carcinogenesis." (PMID 41009512, 2025). "Thus, we examined the signaling pathways by which TIMP-2 stimulates cell proliferation in lung adenocarcinoma cells." (PMID 26556867, 2015). "In this study, we have shown that TIMP-2 growth-stimulatory activity is mediated by c-Src activation followed by activation of FAK, PI 3-kinase/AKT, and ERK1/2 through an MMP-independent mechanism in lung adenocarcinoma cells." (PMID 26556867, 2015). "We examined a mechanism by which TIMP-2 stimulated lung adenocarcinoma cell proliferation, independent of MMP inhibition." (PMID 26556867, 2015).
lung adenocarcinoma (continued). "When lung adenocarcinoma patients from another independent cohort (n = 332; MGH + ACC + Nagoya, GSE13213 and GSE11969) were divided into two groups according to TIMP-2 expression, Kaplan-Meier plots showed significant differences in OS for only pstage I (p < 0.001)." (PMID 26556867, 2015).
lymph node metastasis (11 papers, 2000 to 2023). "In the CRC cohort, Fisher’s exact analysis revealed that there was a significant positive association between low TIMP-2 expression in pathological classification (P = 0.025), depth of invasion (P = 0.003), lymph node metastasis (P < 0.001) and TNM stage (P < 0.001)." (PMID 31293204, 2019). "The univariate Cox regression analysis also showed that age, pathological classification, depth of invasion, lymph node metastasis, distant metastasis, TNM stage, and TIMP-2 or MMP-9 expression were associated with OS of CRC patients." (PMID 31293204, 2019). "The team of Graesslin has found a relation between low TIMP-2 expression and myometrial invasion, lymphovascular space involvement, and lymph node metastasis." (PMID 17894888, 2007). "TIMP-2 in the stroma was found more frequently in tumours with lymphatic invasion and lymph node metastasis (P< 0.05)." (PMID 10901373, 2000). "In addition, our paper demonstrated that there was a significant positive correlation between TIMP-2 immunoreactivity in inflammatory cells and the presence of lymph node metastasis." (PMID 37240178, 2023). "The results of immunohistochemistry analysis showed that the proportion of cells stained positive for TIMP2 in NPC was significantly higher than that in inflammatory tissues, and the proportion of positive cells increased significantly with lymph node metastasis." (PMID 32595725, 2020). "The expression of tissue inhibitor of metalloproteinase-2 (TIMP-2) is lower or negative in patients with lymph node metastasis." (PMID 30959907, 2019). "Additionally, the MMP-2/TIMP-2 ratio was higher in CRC than in normal tissues and gradually decreased with tumor stage, depth of invasion, and lymph node metastasis." (PMID 24395652, 2014).
renal fibrosis (11 papers, 2018 to 2026). A final common manifestation of a wide variety of chronic kidney diseases characterized by glomerulosclerosis and tubulointerstitial fibrosis. "Tubule-specific deletion of TIMP2 markedly attenuated renal fibrosis, suppressed senescence-associated secretory phenotypes (SASP), and promoted tubular repair." (PMID 41606428, 2026). "Kl and Clu contribute antiaging and antifibrotic effects in kidneys and Timp1 and Timp2 participate in remodeling the extracellular matrix, impacting renal fibrosis." (PMID 41567268, 2026). "Genetic deletion of TIMP2 in tubular epithelial cells attenuates renal fibrosis and improves mitochondrial function." (PMID 41606428, 2026). "3‐Deazaneplanocin A (Dznep), an inhibitor of histone modification, suppresses renal fibrosis and the expression of tissue inhibitor of metalloproteinases‐2 (TIMP2), a profibrotic factor, in mouse ischemia–reperfusion models." (PMID 37710084, 2023). "The increased expression levels of renal fibrosis-related genes (Grem2, Id3, Fst, Dcn) and renal damage-related genes (Runx1, Vtn, Clo6a2, Tnxb, Itga8, Timp2, Fgfr2, Fgf9) further supported the idea that miPEP31 deficiency exacerbated Ang II-induced kidney inflammation." (PMID 38992718, 2024). "A previous report has shown that UUO‐induced renal fibrosis was suppressed in TIMP2 knockout mice." (PMID 37710084, 2023). "We also found that T1Col, αSma, Timp-1 and Timp-2 were significantly increased in kidney of the mice receiving Ang II infusion compared to vehicle treated mice, consistent with the presence of renal fibrosis." (PMID 30120363, 2018). "However, there are only few reports about the role of TIMP2 in renal fibrosis and CKD progression." (PMID 37710084, 2023). "Moreover, HIF activation might upregulate the expression of TIMP2 and might be involved in the development of medium‐ to long‐term renal fibrosis." (PMID 37710084, 2023). "After 6 months, the treated group showed increased levels of MMP-2 and MMP-9, reduced levels of TIMP-1, TIMP-2, and TGF-β/Smad signalling, improved renal fibrosis and enhanced renal function." (PMID 37196129, 2023). "To investigate whether SiNPs induce renal fibrosis, we determined the expression levels of MMP-9, MMP-2, TIMP-2, and TGF-β1 in kidney tissue using RT-qPCR." (PMID 38655071, 2024).